CD36 (CD36 molecule (CD36 blood group))
Diseases named in the same sentence as CD36 in open-access papers (continued):
Sharing a sentence is not in itself a finding about the gene and the disease.
tumor (continued). "We also showed that (a) CD36− FBs secrete more activin A, creating a positive feedback loop for tumor progression, and (b) CD36 expression in FBs is reversible once activin A is removed (Supplementary Results)." (PMID 36361532, 2022). "Firstly, higher expression of enzymes related to lipid uptake such as CD36 enables tumor cells to compete with other cells for lipids from TME." (PMID 36172157, 2022). "Deletion or inhibition of CD36 limits the uptake of FAs from the tumor microenvironment and reduces adipocyte-mediated invasion and migration of prostate cancer cells." (PMID 35896782, 2022). "In accordance, mitochondrial respiration was decreased in tumor-treated macrophages from Cd36−/− mice." (PMID 36184646, 2022). "They identified the influence of CD36 mediated fatty acid uptake and increased mitochondrial fatty acid metabolism in promoting survival and anti-tumor activity of Trms." (PMID 35008414, 2022). "We can suggest that in clinical practice, patients with CD36-positive tumours should be closely followed to detect early progression and offer effective alternative treatments as soon as possible." (PMID 35159947, 2022). "Effects on tumor cells are mediated by TSP-1 through the interaction with CD36 as well as CD47, a member of the immunoglobulin superfamily." (PMID 35054787, 2022). "Preclinical studies have reported that treatment with anti-CD36 antibodies significantly exerted anti-tumor or anti-metastatic effects." (PMID 35216285, 2022). "This study also points to a possible contribution of CD36 in promoting drug tolerance, linking CD36 expression with tumor relapse." (PMID 35912100, 2022). "A previous study demonstrated that only 18.8% of ESCC tumour tissues express high levels of CD36 according to the data of IHC staining, and the expression of CD36 is not detected in several ESCC cell lines." (PMID 35735113, 2022). "Disruption of CD36 selectively stimulated intratumoral Treg apoptosis and impaired tumor Treg accumulation and suppressive activity." (PMID 35371055, 2022). "IHC analysis demonstrates that a reduction in CD36 and MMP28 expression is associated with an increase in E-cadherin expression in tumor lesions with CD36 knockdown, as compared to NTC tumor tissues." (PMID 35008415, 2022). "Studies have shown that the increased expression of CD36 in tumor‐infiltrating CD8+ T cells in the TME led to tumor progression and poor survival rates in human and mouse cancers." (PMID 36317423, 2022). "CD36 is highly expressed in diverse tumor types and its expression correlates with advanced stages, poor prognosis, and reduced survival." (PMID 36568966, 2022). "Among patients with tumour progression during the first 12 months after cystectomy, disease-free survival was shorter in CD36-positive tumours than in those CD36-negative (6.51 months (95% CI 5.05–7.96) vs. 8.74 months (95% CI 8.16–9.32); p = 0.049)." (PMID 35159947, 2022). "Anti-CD36 monoclonal antibody promoted the apoptosis of tumor Treg cells in mouse tumor model, and led to a significant increase in tumor infiltration of CD8+ T cells and had a synergistic effect with PD-1 antibody." (PMID 35444235, 2022). "A previous study demonstrated that ablation of CD36-mediated FA uptake attenuated tumor progression." (PMID 36147494, 2022). "The large majority of the high CD36 tumor tissue displays high adipocyte infiltration, suggesting that CD36 participates in the tumor microenvironment (TME) remodeling." (PMID 36568966, 2022). "It has been reported that CD36-mediated uptake of oxidized lipids by leukocytes undermines anti-tumor immune response." (PMID 35991116, 2022). "CD36-KO TAMs lose their tumor proliferation-promoting ability in vitro and vivo and exhibit an M1-macrophage gene signature." (PMID 36115986, 2022). "This suggests that therapy targeting the CD36/ lipid peroxidation axis has the potential to enhance anti-tumor immunity." (PMID 35062950, 2022).
tumor (continued). "CD36 also plays an important role in tumor metastasis, affecting tumor development through different mechanisms." (PMID 36354702, 2022). "CD36 stimulates tumor development and metastasis by allowing cells to take up lipids from the extracellular microenvironment and promoting the oxidation of FAs to create ATP." (PMID 35625633, 2022). "The lipid-enriched vesicles are preferentially partitioned into macrophages via CD36, that fuel macrophages and trigger their tumor-promoting activities." (PMID 36184646, 2022). "The blocking of CD36 restored their anti-tumor activity, which was responsible for inhibiting the Treg activity." (PMID 35812393, 2022). "The negatively charged CLESH structural domain residue in CD36 interacts with the TSR to inhibit tumor angiogenesis." (PMID 36354702, 2022). "The increased uptake of lipid metabolites secreted by CAFs mainly through CD36 expressed on CRC cell membrane enhances the migration of tumor cells." (PMID 36354702, 2022). "Among the separated immune cells, their ability to take up tumor-derived lipids was positively related to CD36 expression." (PMID 36184646, 2022). "CD36 prevents angiogenesis in tumor microvascular endothelial cells by binding to TSP-1 and inducing apoptosis or blocking the vascular EGFR 2 pathway." (PMID 35682652, 2022). "CD36, a scavenger transmembrane glycoprotein receptor, is found in a variety of cell types, including tumour cells, adipocytes, macrophages, and certain epithelial cells." (PMID 36816174, 2022). "Studies have shown that excessive cholesterol in the tumor microenvironment increases the expression of CD36 on effector T cells." (PMID 36387147, 2022). "We further reveal that CD36-dependent metastasis-initiating cells require mitochondrial m5C to activate invasion and dissemination from the primary tumour." (PMID 35768510, 2022). "In response to the TME change, the scavenge receptor CD36, a central regulator for lipid metabolism, is upregulated in tumor-infiltrating macrophages." (PMID 36184646, 2022). "We show that the CD44- and CD36-expressing tumour cells only efficiently metastasize when using mitochondria as an energy source." (PMID 35768510, 2022). "To measure the mitochondrial activity in CD44+CD36+ tumour cells, we first sorted cancer cells for high (H) or low (L) expression of CD44 and CD36, and then quantified the MMP in the different subpopulations." (PMID 35768510, 2022). "For example, the company Ona therapeutics has developed several anti-CD36 antibodies as anti-tumor candidates." (PMID 36568966, 2022). "In fact, when macrophages are cocultured with tumor cells or isolated from the tumor bed, it has been shown that they accumulate lipids and use the CD36 and LOX-1 scavenger receptors to transport FAs from the TME." (PMID 35406621, 2022). "In this process, cholesterol induces CD36 expression on tumor-infiltrating CD8(+) T cells, consequently, CD36 triggers uptake of fatty acids in CD8(+) T cells resulting in ferroptosis." (PMID 36289191, 2022). "Overexpression of CD36 presumably provides the cells with a high amount of FA, and consequently energy, which tumor cells need for invasive growth and metastasis." (PMID 34439279, 2021). "IHC results showed that CD36-positive tumor cells are accompanied by higher PCNA-nuclear expression." (PMID 33771982, 2021). "The differences in CD36 expression in tumor tissue and adjacent normal tissues also displayed the heterogeneity among different cancers illustrated by the RNA-seq data of 8,624 samples in TCGA and GTEx databases." (PMID 34234847, 2021). "Genetic deletion of CD36 in Treg cells led to decreased Treg cell infiltration into tumors and greater anti-tumor immunity." (PMID 34283042, 2021). "As shown in a recent study, tumor microenvironment-derived cholesterol increases CD36 expression and subsequent fatty acid uptake in tumor-infiltrating CD8+ T cells." (PMID 34654454, 2021).
tumor (continued). "One interesting phenomenon is that surgical treatment of tumor-bearing mice upregulates the lipid content of splenic NK cells with high CD36 and low GzmB expression." (PMID 34742349, 2021). "In a previous work, we showed that activin A secreted from tumor epithelial cells decreases CD36 expression in FBs in a coculture assay and that CD36 expression was inversely correlated to the concentration of activin A in a dose-dependent manner." (PMID 34572749, 2021). "The characterization of TSP1 as a potent inhibitor of angiogenesis led to efforts to harness this activity for anti-tumor therapies by targeting CD36." (PMID 33925464, 2021). "Combining anti-PD-1 therapy with an anti-CD36 antibody in a syngeneic mouse melanoma model effectively reduced tumor burden than either agent alone." (PMID 33925464, 2021). "The VM process is multifaceted and our study suggests that CD36 contributes by co-operating with adhesion molecules (such as integrin-α3) to engage with components of the tumor microenvironment (such as laminin)." (PMID 34215227, 2021). "Adipocyte infiltration by tumour cells was present in 128 (71.1%) of tumour tissues, positive CD36 expression was present in 109 (60.5%) of tumour tissues with adipocyte infiltration." (PMID 34561446, 2021). "CD36 expression in cancer cell lines, tumor tissue, and their adjacent normal tissues displayed heterogeneity among different cancers." (PMID 34234847, 2021). "In PCa, extracellular FAs seem to be crucial contributors to lipid synthesis and tumor progression, and the inhibition of FA uptake by CD36 abrogation has been demonstrated to be an effective strategy to reduce tumor growth in preclinical models of PCa." (PMID 33922898, 2021). "In the present study, we found that CD36 is highly expressed in human HCC as compared with non-tumor hepatic tissue." (PMID 33771982, 2021). "CD36 via peroxisome proliferator-activated receptor-β (PPARβ) signalling sustains survival and function in intra-tumour Tregs by modulating mitochondrial fitness and NAD levels, which are critical for metabolising lactate." (PMID 34202553, 2021). "It was also suggested that CD36 plays an essential role in metabolite exchange and symbiosis of the tissue microenvironment, facilitating lipid uptake of tumor cells." (PMID 35029792, 2021). "To verify the expression of phosphatidylserine (PS) recognition receptor on the surface of TAMs, we measured the expression of CD36 in BMDMs treated with tumor debris." (PMID 33809707, 2021). "In turn, cancer cells upregulate the expression of FA transporters (e.g., cluster of differentiation 36 (CD36)), increasing the influx of FAs and providing the tumor with sufficient substrates to sustain growth and progression." (PMID 33922898, 2021). "In tumor tissues, CD36 is expressed by cancer cells, ECs, stromal cells and immune cells with numerous studies supporting the notion that CD36 participates in the progression of cancer." (PMID 34215227, 2021). "This adaptation to lactate appears to be mediated by the specific expression of CD36 at the surface of intra-tumour Tregs." (PMID 34202553, 2021). "A significant reduction in E0771 tumor growth was also observed for CD36 EC-KO mice compared with WT littermates." (PMID 34314388, 2021). "Moderate CD36 staining was observed in 84 (46.7%) of tumour tissues and strong staining was observed in 63 (35%) of tumour tissues." (PMID 34561446, 2021). "Inhibition of CD36, a transmembrane protein that mediates FA uptake, has been shown to suppress tumor growth." (PMID 34766135, 2021). "HO-1-deficient BMDMs exposed to tumor cell debris also exhibited a diminished expression of CD206 and the scavenger receptor CD36 compared to the corresponding wild type (WT) macrophages." (PMID 33809707, 2021).
tumor (continued). "CD36 also directly suppresses the anti-tumor immune function of CD8+ tumor-infiltrating lymphocytes (TILs) by promoting lipid peroxidation through the uptake of oxidized low-density lipoproteins (OxLDL)." (PMID 33801564, 2021). "When the tumor cells were exposed to the CM from CD36+ or CD36− FBs, there was a significant growth suppression or promotion, respectively, in terms of the number of cells." (PMID 34572749, 2021). "Here, we showed that the stiffness microenvironment activates a CD36/AKT/E2F3 mechanosignaling to modulate tumor-promoting factor FGF2 expression." (PMID 34873170, 2021). "Using the TCGA database, we screened 16 tumour cohorts for the top 10 genes that positively correlated with increased CD36 expression." (PMID 34561446, 2021). "Pretreatment of HCC cells with PI3K/AKT/mTOR inhibitors largely blocked the tumor-promoting effect of CD36." (PMID 33771982, 2021). "In this study, we observed that CD36 levels were increased in individual cells or tumor nests in ER+ BC patient specimens." (PMID 34168243, 2021). "Both CD36 expression and tumor grading were independent factors increasing chances for metastasis (for G2 OR = 3.17 and for G3 OR = 47.3)." (PMID 34439279, 2021). "Tumor tissue from the mice injected with silenced lncRNA-SNHG1 cell mixture showed a low level of CD36+ cells." (PMID 34618681, 2021). "In human PCa, CD36 protein was detected in both epithelial and stromal cells and equally expressed in tumor and adjacent normal regions, preventing its use as diagnostic biomarker." (PMID 34386430, 2021). "Similar to VAT Treg cells, tumor-derived Treg cells also upregulate lipid metabolism and CD36 through a PPARβ-dependent mechanism." (PMID 34283042, 2021). "Whereas the expression of integrins on tumor vessels was found to vary with the stage of tumor progression in the Rip-Tag model of pancreatic cancer, CD36 is expressed at all stages." (PMID 33869231, 2021). "FATP4, CD36, and ACSL1 expression in NMIBC tumor tissues revealed a weak positive correlation among them (FATP4 vs. CD36, Spearman rho = 0.273, p < 0.001; FATP4 vs. ACSL1, Spearman rho = 0.378, p < 0.001; CD36 vs. ACSL1, Spearman rho = 0.260, p < 0.001)." (PMID 34257543, 2021). "Hypoxia is a well-known initiator of tumor vascularization and hypoxia has also been documented to elevate CD36 expression on microvascular ECs (MVECs)." (PMID 34215227, 2021). "We demonstrated the role of adipocytic and endothelial CD36 in promoting tumor growth and chemoresistance conferred by adipose tissue–derived LCFAs." (PMID 34314388, 2021). "CD36 is a scavenger receptor that mediates lipid uptake, is expressed in multiple cancer types, and accelerates tumor growth." (PMID 34572749, 2021). "Specifically, programmed celldeath dependent on iron and characterized by the accumulation of lipid peroxides(ferroptosis) was found to occur in CD36-expressing tumor-infiltrating CD8+ Tcells." (PMID 34603769, 2021). "Taken together, these findings begin to reveal an important inter-relationship between cancer cells, tumor ECs and CD36." (PMID 34215227, 2021). "CD36 mediated fatty acid uptake and oxidation in tumor cells, and also regulated glucose metabolism in the liver and muscle as reported by ours and others studies." (PMID 33771982, 2021). "CD36 drives tumor progression in glioblastoma, melanoma, oral, and other carcinomas and it is required for stem cell self-renewal, tumor initiation, and metastatic potential in preclinical models." (PMID 34386430, 2021). "CD36 is selectively expressed on intratumoral regulatory T cells and enables them to metabolically adapt to the lactic-acid enriched tumor microenvironment by increasing fatty acid uptake." (PMID 33925464, 2021). "We found that tumor-infiltrating CD33high cells showed high gene expression levels of CD36, CD14, FUT4 (CD15), CD80, CD86, CSF1R and immune checkpoint ligand genes including CD274 (PD-L1), LGALS9 (galectin-9), PVR and VSIR." (PMID 33000418, 2021).
tumor (continued). "In contrast, expression of GLUT1, the main tumor glucose transporter, was markedly increased in both CD36-KO models." (PMID 34314388, 2021). "Further studies of CD36 showed the involvement in tumor cell metabolism, metastasis, immune escape, and therapy resistance with respect to radio- and chemotherapy." (PMID 34439279, 2021). "In correlation with the importance of balanced lipid homeostasis, the complex pan-cancer analyses of the prognostic role of CD36 overexpression have been published recently and highlighted the tumor type–dependent increase in CD36 expression." (PMID 35029792, 2021). "This was an extension of earlier results that increased production of activin A by tumor cells downregulating the CD36 expression in FBs, which induces the FBs to secrete more activin A and to initiate a positive feedback loop." (PMID 34572749, 2021). "Taken together, these data suggested that APOC2 cooperated with CD36 to promote tumor progression and PM in GC." (PMID 34459127, 2021). "Inhibition of FASN has been observed to upregulate expression of CD36, which can compensate for the anti-tumor effects of FASN inhibition." (PMID 33514004, 2021). "Usage of the CD36-neutralizing antibodies to inhibit fatty acid receptor CD36 leads to therapeutically suppression of tumor growth and metastasis in oral squamous cell carcinomas." (PMID 34095111, 2021). "We found that a subset of CD44+ BCSCs with high expression levels of PKD-1 and CD36 were localized within or near blood vessels and tumor nests." (PMID 34168243, 2021). "Cisplatin reduced tumor growth by only 2-fold in WT mice, whereas in CD36 EC-KO mice treated with cisplatin, tumor growth was almost completely blocked." (PMID 34314388, 2021). "As a typical fatty acid transporter, saturated and monounsaturated fatty acids promote tumor proliferation and migration via a CD36-dependent pathway." (PMID 33771982, 2021). "This shows that FA metabolism via CD36 uniquely shape metabolic adaptation which supports the functionality of tumor‐infiltrating Treg cells." (PMID 33067808, 2020). "Involvement of CD36 in the metastatic process is related to the three components of any tumor niche: the tumor cells, the stromal cells, and the endothelial cells." (PMID 32781778, 2020). "CD36 is found frequently dysregulated in various cancers affecting the tumor cell metabolism, survival, proliferation, and metastasis." (PMID 33050166, 2020). "We believe that these two tumors arose from one primary tumor with viral integration into CD36 that underwent clonal expansion and was subsequently established in the other tonsil." (PMID 32954225, 2020). "CD36 is expressed in tumor tissues, not only by tumor cells, but also by stromal, immune cells, and MVECs, and depends on tumor stage and cell type." (PMID 32781778, 2020). "Using the same TMA, we assessed the expression of CD36 levels in tumor tissues and found that expression was significantly higher as compared to normal colon mucosa as determined by statistical evaluation of immunoreactivity scores." (PMID 32850342, 2020). "HCT116, HT29, and HT29 LuM3 cells (NTC and shRNA-mediated CD36 knockdown cell lines) were injected subcutaneously into Nu/Nu mice and tumor growth was measured." (PMID 32850342, 2020). "A high olive oil diet aggravated growth and metastasising of He-La xenografts in mice; tumour progression correlated with CD36 expression." (PMID 32526973, 2020). "In PF-A tumor slides, analysis of top signature genes demonstrated mutually exclusive expression of PF-Ependymal-like (CD36) and PF-NSC-like (ATF3) markers, and some extent of spatial clustering of cells expressing the corresponding programs." (PMID 32663469, 2020). "CD36 expression was induced in cancer cells co-cultured with adipocytes in the context of ovarian cancer, leading to increased tumor cell fatty acid uptake, invasion and proliferation." (PMID 33604295, 2020).